IL1B (interleukin 1 beta)
Diseases named in the same sentence as IL1B in open-access papers (continued):
Sharing a sentence is not in itself a finding about the gene and the disease.
neurodegenerative disease (continued). "Increased levels of TNFα, IL-6, IL-1β, and MCP1 have been reported in the CSF of AD and PD patients and susceptibility to neurodegenerative disease." (PMID 40507859, 2025). "For example, an increase in IL1β levels can weaken the strength of synaptic transmission between hippocampal CA1 neurons, a process implicated in the progression of neurodegenerative diseases such as multiple sclerosis." (PMID 40825935, 2025). "As with other neurodegenerative disease–associated proteins, aggregates of TDP-43 were found to act as an efficient activating signal to license NLRP3-induced IL-1β release in microglia." (PMID 41386298, 2025). "Lowering the levels of TNF-α, IL-6, and IL-1β can prevent the development and progression of inflammatory and degenerative diseases." (PMID 41471283, 2025). "Elevated levels of proinflammatory cytokines such as IFN‐γ, IL‐1β, IL‐6, IL‐18, and TNF‐α have been shown to induce tau hyperphosphorylation and neuronal loss in AD and other neurodegenerative diseases." (PMID 38923171, 2024). "In neurodegenerative diseases, microglia contract their protrusions and migrate toward the site of injury, where they release pro-inflammatory cytokines such as IL-1β, TNF-α, and IL-6." (PMID 38649885, 2024). "IL-1β, a key regulator of neuroinflammation secreted by activated microglia, has been shown to promote the progression of various neurodegenerative diseases and impair learning and memory functions." (PMID 39239519, 2024). "C3 is induced in most neurodegenerative diseases and is upregulated by proinflammatory cytokines such as IL-1β (25, –, 28)." (PMID 37191498, 2023). "Pro-inflammatory cytokines, such as TNF-α, IL-6 and IL-1β, play a crucial role in the pathophysiology of neurodegenerative diseases." (PMID 37521470, 2023). "Previous studies have shown that neurodegenerative diseases, including AD, are mediated by inflammation and neurotoxic factors, such as interleukin-1beta (IL-1β), tumor necrosis factor-alpha (TNF-α), reactive oxygen species (ROS), and NFκB activation." (PMID 37056359, 2023). "Under various neurodegenerative disease conditions, activated microglia release inflammatory cytokines and neurotoxic substances such as IL-1β, IL-6, TNF-α, and nitric oxide (NO), resulting in progressive neuronal degeneration in PD." (PMID 38138478, 2023). "Third, the activation of microglia and astrocytes induced by damage-associated molecular patterns (DAMPs) results in an increased release of the inflammatory cytokines TNF-α, IL-1β and IL-6 in cerebellum, which mediates neurodegenerative diseases." (PMID 37626842, 2023). "Complement component 3 (C3) is also induced in neurodegenerative diseases and is upregulated by proinflammatory cytokines such as IL-1β, gamma interferon (IFN-γ), and tumor necrosis factor alpha (TNF-α) (25, –, 28)." (PMID 37191498, 2023). "Interleukin-1β (IL-1β) is one of the most extensively studied cytokines involved in neuroinflammation and neurodegenerative diseases." (PMID 37191498, 2023). "TNF-α, IL-1β, and β-EP play a key role in neurodegenerative diseases, mainly by regulating the release of inflammatory factors from glial cells, and inducing the expression of signaling-related transcription factors." (PMID 36903325, 2023). "Activated microglia can secrete large amounts of inflammatory cytokines, such as NO, IL-1β, TNF-α, etc., leading to a neuroinflammatory cascade that causes neuronal death and neurodegenerative diseases, including AD." (PMID 37895939, 2023). "Reactive microglia and astrocytes release pro-inflammatory cytokines, such as tumor necrosis factor alpha (TNF-α) and interleukin-1 beta (IL-1β), which leads to glutamate neurotoxicity and neuronal death, events related to neurodegenerative diseases." (PMID 36221097, 2022). "Previous studies have shown that IL-1β induces astrocyte inflammatory gene expression to levels that match neuroinflammation seen in various neurodegenerative diseases." (PMID 35326266, 2022).
neurodegenerative disease (continued). "Production of IL-1β in the microglia is the initiating step of nerve inflammation, which drives the amplification of inflammatory cascade and pathogenesis of neurodegenerative disease." (PMID 36408278, 2022). "Our recent results show that IL-1β induces inflammatory gene expression and metabolic changes in astrocytes in ways that are consistent with neurodegenerative diseases." (PMID 35326266, 2022). "Among the various types of inflammasomes, NLRP3 inflammasome is the well-known in neurodegenerative diseases, especially in AD and PD and the activation of the NLRP3 inflammasome causes the production of IL-1β and IL-18 in microglia cells." (PMID 34922574, 2021). "In particular, IL-1β, IL-6, and TNF-α are representative pro-inflammatory cytokines associated with various degenerative diseases." (PMID 34234892, 2021). "A study performed on neurodegenerative disease murine models indicated that cannabidiol decreased the level of pro-inflammatory cytokines, including IL-1β, in the central nervous system." (PMID 33673103, 2021). "C3 is inducibly expressed in astrocytes of most neurodegenerative diseases by inflammatory cytokines such as IL-1β, IFN-γ, and TNF-α." (PMID 34530848, 2021). "We also studied TNF-α and IL-1β, which are well-known inflammatory markers playing a key role in neurodegenerative disease." (PMID 34699347, 2021). "In neurodegenerative diseases, IL-1β is considered one of the main culprits for infiltration of neutrophils, shattering of the BBB, astrogliosis, and neovascularization." (PMID 34691061, 2021). "Another important point to understand the role played by IL-1β liberated through NLRP3 activation in neurodegenerative diseases, is to characterize in detail the inflammasome expression and activation in CNS inflammatory cells." (PMID 33353046, 2020). "Our study not only identified a novel role of IL-1β in the pathophysiology of endotoxemia-elicited neuroinflammation but also suggested a new strategy for developing potential therapies for neurodegenerative diseases." (PMID 32070376, 2020). "Through this route, the development of local and systemic inflammation occurs involving the release of pro-inflammatory mediators such as IL-1β, among others contributing to neurodegenerative diseases such as Alzheimer’s and Parkinson’s diseases." (PMID 32576879, 2020). "Implication of IL-1β in neurodegenerative diseases is well known because of the important role of neuroinflammation in these pathologies as well as well as the importance of oxidative stress." (PMID 31627485, 2019). "Taken together, these excess IL-1β-driven events work toward P-parkin-mediated ubiquitination, which has been shown to be neuroprotective in numerous models of neurodegenerative diseases." (PMID 31882005, 2019). "Recent studies have shown that levels of IL-1β and IL-18 in the brain tissue, plasma and CSF in patients with neurodegenerative diseases, brain injury and CNS infection are elevated, suggesting that IL-1β and IL-18 are involved in neuroinflammation." (PMID 31681133, 2019). "IL-1β and inflammasome have been implied in other neurodegenerative diseases like ALS or virus infection." (PMID 31627485, 2019). "Researches in recent decades illuminated that IL-1β accelerates the pathogenesis of neurodegenerative diseases and diabetic complications." (PMID 29507694, 2018). "NLRP3 inflammasome is the main regulator to produce IL-1β and is considered to regulate the progression of several neurodegenerative diseases." (PMID 30107806, 2018). "In CA1 SR of 6 months old transgenic mice, we found significantly higher levels of the expression of the cytokines TNF-α, IL1β, as well as iNOS in astrocytes, confirming our and others’ results in TgCNRD8 mice and other models of neurodegenerative diseases." (PMID 30483118, 2018).
neurodegenerative disease (continued). "Increasing evidence implicates the NLRP3 inflammasome and its activation/release products; ASC specks, caspase-1 and IL-1β in the pathogenesis of neurodegenerative disease and stroke." (PMID 29654318, 2018). "Altogether, these findings indicate the detrimental role of high concentrations of TNF and IL-1β in both forms of synaptic plasticity during neuroinflammatory and neurodegenerative diseases." (PMID 29861718, 2018). "Increasing evidence has demonstrated that the proinflammatory factors such as NO, IL-1β, and TNFα contributed to neurodegenerative diseases." (PMID 29576855, 2018). "On the other hand, the nucleotide-binding oligomerization domain-like receptor containing pyrin domain 3 (NLRP3) inflammasome is an essential regulator to produce IL-1β and is considered to regulate the progression of several neurodegenerative diseases." (PMID 30107806, 2018). "This suggests that IL-1β is a critical inflammatory factor involved in neuroinflammatory and neurodegenerative diseases." (PMID 29885667, 2018). "As proinflammatory and neuro-toxic cytokines, IL-1β and TNF-α are secreted by M1 phenotype microglia and cause neuronal cell death in most neurodegenerative disease." (PMID 30607245, 2018). "Under abnormal conditions, such as in neurodegenerative disease, microglia can be over-activated in the CNS, and the over-activation of microglia can produce excessive proinflammatory cytokines, especially IL-1β." (PMID 30189852, 2018). "Pro-inflammatory cytokines, which include IL-1β, IL-6, and TNF-α, are believed to moderate neuroinflammation and cause cell death in different neurodegenerative diseases." (PMID 28490320, 2017). "The activation of microglia cells can produce NO, PGE2, TNF-α, IL-1β, and IL-6, which can contribute to the inflammatory reaction in neurodegenerative diseases." (PMID 29267220, 2017). "Elevated levels of IL-6, IL-1β and TNFα often found in the blood of both AD and PD patients can be considered as the evidence of systemic inflammation accompanied both of these neurodegenerative diseases." (PMID 29211044, 2017). "Neurodegenerative diseases are always accompanied by chronic neuroinflammation with the excessive production of IL-1β and IL-18 pro-inflammatory cytokines, which has detrimental consequences for brain structure and function." (PMID 28337127, 2017). "IL-1β has been regarded as a critical inducer in the pathogenesis of neurodegenerative diseases, including AD and PD." (PMID 27084336, 2016). "IL-1β plays an important role in this response; yet its production and mode of action in the brain are not fully understood and its precise implication in neurodegenerative diseases needs further characterization." (PMID 26091541, 2015). "We have analyzed chemokines CCL2, CCL5 and IL-8; as well as cytokines TNF-α and IL-1β as they are known to be involved in the pathogenesis of neurodegenerative diseases including PD." (PMID 26275153, 2015). "In view to understand the role played by IL-1β in neurodegenerative diseases, it is important to characterize in detail the inflammasome expression and activation in CNS inflammatory cells." (PMID 26091541, 2015). "For instance, microglia can compromise the neurogenic cascade during chronic stress, aging, and neurodegenerative diseases, by their release of proinflammatory cytokines such as IL-1β, IL-6, and TNFα." (PMID 24772353, 2014). "Different groups have demonstrated that the inflammatory cyclooxygenase-2 (COX-2), inducible nitric oxide synthase (iNOS) and cytokines, such as interleukin (IL)-1β, IL-6 and tumor necrosis factor (TNF)-α, are associated with neurodegenerative diseases." (PMID 22214188, 2012). "Our finding of NPC migration to inflammatory cytokine IL-1β also suggests the potential therapeutic application of NPC transplantation in neurodegenerative diseases." (PMID 23210607, 2012).
neurodegenerative disease (continued). "For example, HIV-1 infected macrophage and DCs are important suppliers of proinflammatory cytokines, including TNF-α, IL-6 and IL-1β, which are etiologically relevant to HIV-1 associated neurodegenerative diseases (HAND)." (PMID 22693544, 2012). "BBB damage has been seen in many neurodegenerative diseases and animal models of seizure, and studies have shown that pro-inflammatory cytokines including TNF-α, IL-1β, IL-6, and interferon-λ are implicated in the regulation of BBB permeability." (PMID 21777430, 2011). "Interleukin-1β (IL-1β) is a pro-inflammatory cytokine that contributes to neuronal injury in various degenerative diseases, and is therefore a potential therapeutic target." (PMID 21314939, 2011). "Aside from neurodegenerative diseases, IL-1β levels are elevated after mechanical damage to the CNS." (PMID 22200088, 2011). "Furthermore, pro-inflammatory cytokines such as IL-1β and TNF-α have been implicated in the pathogenesis of neurodegenerative diseases such as experimental autoimmune encephalomyelitis (EAE), multiple sclerosis (MS) and PD." (PMID 39766497, 2024). "Brain macrophages produce and respond to cytokines that can contribute to apoptosis and neuronal injury, including the pro-inflammatory cytokine interleukin-1 beta (IL1β) which is associated with neurotoxicity in PWH and in aging-related neurodegenerative diseases." (PMID 39459844, 2024). "In neurodegenerative diseases and neuroinflammation, the accumulation of misfolded proteins, such as beta-amyloid and alpha-synuclein, can lead to inflammasome activation, resulting in the release of interleukin (IL)-1β and IL-18." (PMID 39710713, 2024). "Some studies reported that TNF-α and IL-1β could stimulate actin and played an important role in the process of neurodegenerative disease." (PMID 35866065, 2022). "IL-1β is related to the pathogenesis of neurodegenerative diseases and other diseases." (PMID 35053883, 2022). "Elimination of mitophagy has been indicated that it resulted in damaged mitochondria signals, such as the accumulation of mitoROS and damaged mitochondria, thus leading to pyroptosis and the release of IL-1β, which contributes to the progression of neurodegenerative diseases." (PMID 36615696, 2022). "Cultured microglia initiate a robust proinflammatory response when exposed to LPS, an agonist of toll-like receptors, resulting in an altered gene signature and release of proinflammatory cytokines (e.g., IL1b, TNF, and IL6), which are implicated in neurodegenerative diseases." (PMID 35526014, 2022). "High levels of IL-1β and IL-18 are found in a variety of neurodegenerative diseases." (PMID 34943020, 2021). "In addition, we evaluated the effects of platycodigenin on the LPS-induced production of TNF-α, IL-6, IL-1β, and IL-10, which are important in neuroinflammation and neurodegenerative diseases." (PMID 31487775, 2019). "However, the ubiquitination of undigested aggregates in neurodegenerative diseases characterized by neuroinflammation and elevated IL-1β provides evidence that autophagy is, nevertheless, compromised." (PMID 31882005, 2019). "Furthermore, evidence for inflammasome activation in patients with neurodegenerative disease often relies on detection of higher IL‐1β transcript levels and/or increased gene and protein expression of inflammasome components." (PMID 31015277, 2019). "Hence, increased levels of IL‐1β and IL‐18 are often observed upon CNS infection, brain injury, and neurodegenerative diseases." (PMID 31015277, 2019). "IL-1β, a pro-inflammatory cytokine, plays an important role in the development of inflammatory responses and cell death in the brain against various CNS insults, such as acute injury and neurodegenerative diseases." (PMID 31117242, 2019). "IL-1β is also known to be a key mediator of neuronal function, glial activation, and immune cell recruitment as well as neurodegeneration in CNS injury models and neurodegenerative diseases." (PMID 31440141, 2019).
neurodegenerative disease (continued). "Studies had shown that IL-1β could accelerate the pathogenesis of neurodegenerative disease and DM complications, and the increment of hippocampal IL-1β expression level is related to cognitive and emotional alterations in diabetic mice." (PMID 30524286, 2018). "Therefore, we will review current findings about the role of TNF and IL-1β in animal models of neuroinflammatory conditions and of neurodegenerative diseases, the latter characterized by chronic inflammation." (PMID 29861718, 2018). "2-arachidonoyl glycerol (2-AG), the most abundant endocannabinoid, has been illustrated to play a significant role in protecting neurocytes from inflammatory injuries, such as stimuli of interleukine-1 beta (IL-1β), lipopolysaccharide (LPS), and β-amyloid in models of neurodegenerative diseases." (PMID 30075820, 2018). "In contrast, the levels of IL-6, IL-1β and TNFα in the blood appear to be elevated in patients with both AD and PD, which is the evidence of systemic inflammation that accompanies both of these neurodegenerative diseases." (PMID 29211044, 2017). "In addition, IL-1β is a key pro-inflammatory cytokine that drives neuroinflammatory processes in a variety of neurodegenerative diseases and exerts neurotoxic effects." (PMID 27793054, 2016). "In addition, it is worth noting that IL-1β is considered to contribute to neurotoxicity in several neurodegenerative diseases." (PMID 22523545, 2012). "Thus, elevated activity and/or expression of iNOS, COX-2, MMP-9, IL-1β and TNF-α in brain cells have been implicated in the cascade of events leading to neurodegenerative diseases." (PMID 22018032, 2011). "IL-1β is an inflammatory cytokine produced by macrophages and neutrophils that participate in the pathogenesis of various diseases, such as autoimmune, autoinflammatory, metabolic, and neurodegenerative diseases, contributing to the severity of the pathological process." (PMID 41200163, 2025). "Similarly, antibodies for IL-1β, which have been approved for the treatment of neurodegenerative diseases, have demonstrated significant individual differences in efficacy, and long-term safety has not been fully verified, weakening their potential for clinical use." (PMID 39710713, 2024). "In addition to its role in general inflammation, IL-1β plays a potential, but controversial, role in neurodegenerative disease development as results remain inconsistent between studies, some supporting increased and some showing unaltered IL-1β levels or expression in Alzheimer patients." (PMID 37445700, 2023). "The upregulation of pro-inflammatory cytokines genes (tnfα, cox2b and il1b) and of csfr1a suggests a pro-inflammatory activation of microglia, leading to a detrimental phenotype, sometimes called disease-associated microglia (DAM), which is described in several neurodegenerative diseases." (PMID 35743315, 2022). "Our results showing that appropriate doses of hNSC-EV treatment can modulate the release of proinflammatory cytokines TNF-α and IL-1β by activated human microglia suggests that such EVs could be used for treating neuroinflammation in neurodegenerative diseases." (PMID 35656007, 2022). "Given that mature IL-1β secretion has been shown to be a key mediator in inflammation-induced neuronal apoptosis in neurodegenerative disease, our mechanistic finding suggests that pharmacological inhibition of NLRP3 may alleviate inflammation through Caspase 1 dependent mature IL-1β secretion." (PMID 35431795, 2022). "It has been reported that in neuroinflammation-mediated neurodegenerative diseases, nucleotide binding and oligomerization domain-like receptor pyrin domain contain three activated inflammatory bodies and microglia as well as released inflammatory cytokines such as IL-1β play important roles." (PMID 34135761, 2021). "In addition, due to IL-1β inhibition, CGs could also be beneficial in neuroinflammation and, thus, they represent a hope for the treatment of neurodegenerative diseases." (PMID 33947098, 2021).